IL6 (interleukin 6)
Diseases named in the same sentence as IL6 in open-access papers (continued):
Sharing a sentence is not in itself a finding about the gene and the disease.
lung carcinoma (continued). "Similarly, IL-6 expressed by tumor-associated macrophages (TAMs) in KRAS driven lung cancer model causes activation of STAT3 pathway with tumor progression." (PMID 33352869, 2020). "The decreased levels of interleukin-6 and tumor necrosis factor-α may be associated with lower risk of lung cancer." (PMID 30723700, 2019). "Increased levels of IL6 induce the expression of anti-apoptotic proteins that inhibit apoptosis and promote proliferation in cells, which in turn are associated to mediate resistance to chemotherapy in prostate, breast and lung cancer cells." (PMID 30678647, 2019). "For instance, IL-6 was associated with poorer survival in both African-American and White lung cancer patients, while IL-10 and IL-12 were associated with poorer survival only among African-American lung cancer patients." (PMID 31448052, 2019). "Moreover, as IL-6 is a key regulator of muscle mass during cachexia and has been associated with worse prognosis in lung cancer patients, we compared the prognostic value of IL-8 with IL-6 using KM plotter server." (PMID 31455042, 2019). "Interestingly, our recent work demonstrated that while IL-6 is associated with lung cancer diagnosis in both EAs30 and AAs31, the effect size was considerably larger among AAs, which is further evidence that this IL-6/JAK2/STAT3 pathway is important among AAs." (PMID 31844068, 2019). "Conversely, in a mouse model, chemoprevention of lung cancer was associated with reducing IL-6." (PMID 30365491, 2018). "Because IL-6 in the tumor-associated microenvironment is not only expressed by M2 macrophages but also by cancer cells themselves, we assessed IL-6 levels in lung cancer cells after USP24 knockdown." (PMID 30266897, 2018). "Meanwhile, IL6 is associated with cancer development, including lung cancer." (PMID 29970138, 2018). "Elevated levels of IL-6 have been previously linked to poor lung cancer survival." (PMID 28402963, 2017). "Reports have suggested that elevated levels of IL-6 are mechanistically linked to poor cancer prognosis via IL-6-induced activation of miR-21 via the activation of the STAT3 pathway —miR-21 has been associated with poor survival in lung cancer in multiple studies." (PMID 28402963, 2017). "Previous study also revealed that Met in combination with first-generation TKI effectively increased the sensitivity of TKI-resistant lung cancer cells and blocked tumor growth in xenografts, associated with decreased IL-6 secretion, reversal of EMT and dampened IL-6/STAT3 signaling." (PMID 29312591, 2017). "Two other studies found that increased levels of IL-6 were associated with major depression in patients with lung cancer and pancreatic cancer; the latter study also found an association between the cytokines IL-1β, IL-4, and IL-12(p70) and pain intensity, and between TGF-β and fatigue." (PMID 28542626, 2017). "Also, IL-6 levels are significantly elevated in lung cancer patients, associated with poor prognosis." (PMID 27107418, 2016). "We assessed whether single nucleotide polymorphisms (SNPs) in the IL6 promoter are associated with lung cancer in former uranium miners with high occupational exposure to radon gas." (PMID 26372664, 2016). "Upregulation of the IL-6/STAT3 pathway is associated with lung cancer progression." (PMID 26517240, 2015). "Upregulation of the IL-6/STAT3 pathway is associated with lung cancer progressions." (PMID 26517240, 2015). "Therefore, in the present study, we aimed to perform a meta-analysis to clarify the association between IL-6 rs1800796 polymorphism and risk of lung cancer." (PMID 24984610, 2014). "Our meta-analysis has assessed the relation between CRP, IL-6 and lung cancer risk." (PMID 22912790, 2012). "Notably, IL-6 is also associated with chemotherapy resistance and prognosis in lung cancer patients; studies have shown that IL-6 can activate and enhance chemotherapy resistance in lung cancer by activating the ATM/NF-κB pathway." (PMID 40304000, 2025).
lung carcinoma (continued). "In lung cancer, genetic variants in cytokine genes, such as IL6, IFNG, and TGFβ1, have been found to be associated with an increased severity of CRS after treatment with PD-1 inhibitors, suggesting that these biomarkers may help to predict the exacerbated inflammatory response." (PMID 40004863, 2025). "Therefore, the overall findings could suggest the significance of IL-1β rs16944 and IL-6 rs1800795 as independent risk factors for the development of lung cancer." (PMID 38103126, 2024). "Thus, IL-6 levels are linked with lung cancer bone metastasis in smoker." (PMID 38993553, 2024). "Moreover, lung cancer patients with high expressions of IL-6, Panx1, or both IL-6 and Panx1 genes were associated with poorer overall survival than those having low expression levels of IL-6, Panx1, or both IL-6 and Panx1, respectively." (PMID 37385076, 2023). "A number of studies in patients with lung cancer treated with radiation suggest that elevated IL-1B, IL-6, IL-8, TNF-a, and/or TGF-B1 may associate with radiation-induced pneumonitis and/or fibrosis; however, less evidence is available concerning injury to the heart." (PMID 37796395, 2023). "Moreover, IL-6 is associated with poor prognosis of lung cancer patients." (PMID 35111682, 2021). "Higher IL-6, IL-8, and IL-11 levels were found to be associated with worse survival in patients with cancer, whereas elevated IL-10 and IL-6 levels might be markers of a favorable prognosis for colorectal cancer and lung cancer, respectively." (PMID 33912192, 2021). "Moreover, IL-6 promoter variant was associated with lung cancer in uranium miners." (PMID 29165116, 2017). "Furthermore, (a) the high DNA methylation status of IL promoters in lung cancer cells or tissues was associated with low mRNA levels; and (b) an inverse correlation between DNA methylation of IL-1β, IL-6 and IL-8 gene promoters and their corresponding mRNA levels was observed." (PMID 25590298, 2015). "In addition, some studies suggested that IL-6 rs1800796 might be associated with risk of lung cancer; however, the results have been inconsistent." (PMID 24984610, 2014). "However, IL-6 is also associated with increased risk of lung cancer." (PMID 24260500, 2013). "It is suggested that circulating IL-6 may be associated with lung cancer because it is expressed in premalignant epithelial cells, and the expression is associated with a poor prognosis in lung cancer patients." (PMID 22912790, 2012). "Exposure of THP-1-CS stimulated migration and invasion of A549 lung cancer, and neutralization of IL-6 and IL-1β reduced these pro-migratory effects, confirming cytokine involvement." (PMID 42075013, 2026). "Intervention of the CSF1/CSF1R and IL-6/IL-6R ligand-receptor pairs significantly reduced the ability of CHI3L1 lung cancer cells to recruit macrophages." (PMID 41362730, 2026). "For instance, Siltuximab is an IL-6 inhibitor that fully eliminates IL-6 signal transduction in vivo and in vitro, effectively inhibiting lung cancer proliferation." (PMID 40407951, 2025). "In early-stage lung cancer, N1-TANs are mainly localised to the tumour periphery, where they secrete GM-CSF and IL-6 to activate cytotoxic T lymphocytes (CTLs), thereby mediating tumour suppression." (PMID 41451221, 2025). "This is assisted through the anti-inflammatory effects of IL-6 and IL-17 that have been evident in inducing invasive events in lung cancer cells, creating a hypoxic TME and therefore the immune resistance." (PMID 41376623, 2025). "In order to ascertain the function of Lnk in human MDSCs, PBMCs from lung cancer patients were cultured in the presence of human GM-CSF and IL-6 for two days before being infected with control or human Lnk (hLnk) shRNA-encoding lentiviruses." (PMID 40796725, 2025). "IL-6, IL-7, IL-10, and IL-17A levels were elevated in the plasma of lung cancer patients as compared to those in healthy controls; thus, indicating higher concentrations of inflammatory mediators in patients." (PMID 40040705, 2025).
lung carcinoma (continued). "In a lung cancer mouse model, secretion of IL-6 by KRAS-mutant tumor cells correlated with increased numbers of M2 TAMs and tumor growth." (PMID 40524071, 2025). "Recent research has highlighted the pivotal roles of IL-6 and IL-8 in the development and progression of lung cancer." (PMID 40227646, 2025). "Perioperative platelet counts and inflammatory markers, particularly IL-6, significantly influence wound healing in lung cancer surgery." (PMID 41170644, 2025). "It slows down lung cancer progression by regulating the amount of lung cancer stem‐like cells and IL‐6 expression in the TME." (PMID 40665579, 2025). "At the clinical settings, the combined elevation of IL-6/17 serves as a stronger prognostic marker for poor survival and progression free survival in patients with lung cancer." (PMID 41376623, 2025). "The activation of the IL6/IL6ST/JAK/STAT3 pathway contributes significantly to lung cancer development, including tumor growth, angiogenesis, and malignant progression." (PMID 39840666, 2025). "Further studies based on mouse lung cancer models and human cancer cell lines demonstrated that TBK1 signaling-regulated CCL 5 and IL-6 promote KRAS-driven NSCLC by affecting lung cancer cell proliferation and the local inflammatory microenvironment." (PMID 40076567, 2025). "Autocrine secretion of IL-6 enhances the communication between lung cancer cells and fibroblasts by forming a positive feedback loop with TGFβ, thereby promoting EMT." (PMID 41429896, 2025). "Treatment with 8PN reduced CD318 protein levels and malignant behavior by increasing IL-6 and IL-8 expression, which in turn promoted neutrophil infiltration and enhanced cytotoxicity against lung cancer cells." (PMID 40725832, 2025). "Upon treatment with IL-6, immunofluorescence studies revealed that all three lung cancer cell lines H1299, A549, and H1975 demonstrated significant alterations in the expression levels of several key markers as compared with their control counterparts." (PMID 41378291, 2025). "The results showed that the transcription levels of IL-6 in lung cancer cells were significantly increased." (PMID 41254082, 2025). "In the clinical setting, numerous studies have evaluated the role of circulating IL-6 in patients with lung cancer treated with RT." (PMID 40746594, 2025). "Some studies have found a correlation between elevated IL-6 levels and the severity of cachexia and poor prognosis in patients with lung cancer." (PMID 40519290, 2025). "Compared with a placebo, n-3 LCPUFA supplementation reduced plasma concentrations of IL-6 in breast (P < 0.001) and lung cancers (P < 0.05)." (PMID 40523478, 2025). "In lung cancer patients with carcinomatous pleurisy, the levels of IL-6 and IL-8 are higher, and the soluble form of sIL-6R is lower in effusion fluid compared to normal individuals." (PMID 40136649, 2025). "Specifically, IL-6 has been associated with tumor proliferation in non-small-cell lung cancer (NSCLC), while IL-8 has been identified as a key growth factor in lung cancer." (PMID 40227646, 2025). "Interaction between these adipocytes and lung cancer cells increase secretion of IL-6 by the former cells, which enhances inflammation during cancer development." (PMID 40136652, 2025). "IL-6 levels are increased in a wide range of cancers, including multiple myeloma, lung cancer, colorectal cancer, renal cell carcinoma, and cervical cancer." (PMID 40156608, 2025). "M1-like macrophages typically exert anti-tumor effects by secreting proinflammatory factors such as IL-6/TNF-α in CRC and prostate cancer (PCA), IL-1α/IL-6 in lung cancer." (PMID 40380196, 2025). "Our findings indeed indicate a correlation between IL6 expression and the aggressive progression of lung cancer." (PMID 40361912, 2025). "Tocilizumab, an anti-IL-6 receptor antibody, has demonstrated symptom improvement in cachectic lung cancer patients overexpressing IL-6." (PMID 40519290, 2025).
lung carcinoma (continued). "Pro-inflammatory cytokines such as IL-6 and IL-8 are frequently elevated in lung cancer and contribute to tumor progression by promoting angiogenesis, proliferation, and immune evasion." (PMID 41303495, 2025). "Blockade of IL-6 in mice has been shown to significantly inhibit lung cancer progression, tumor cell–intrinsic STAT3 activation, tumor cell proliferation, and angiogenesis." (PMID 40746594, 2025). "IL-6 also affects the metastatic potential of lung cancer cells by activating the JAK2/STAT3 signaling pathway, which impacts angiogenesis by increasing the expression of VEGF and bFGF." (PMID 40136652, 2025). "TNF-α, IFN-γ, TGF-β, vascular endothelial growth factor, and ILs (e.g., IL-6, IL-17, IL-8, IL-10, IL-22, IL-1β, and IL-18) are the most relevant cytokines involved in lung cancer." (PMID 40136649, 2025). "Co‐cultivation of THP‐1‐derived macrophages with A549 and H1299 lung cancer cells in vitro revealed that the IL‐6 system greatly aided the EMT process in NSCLC cancer cells via the IL‐6‐dependent COX‐2/PGE‐2 signaling pathway regulation." (PMID 39927632, 2025). "In this review, we showed that circulating levels of IL-6, IL-8, and TGF-β1 in the blood of patients with lung cancer treated with RT were consistently negatively associated with survival and RT-related toxicity." (PMID 40746594, 2025). "Histone alterations and DNA methylation can control inflammatory pathways in lung cancer, whereas epigenetic modification and IL-6/STAT3 enhance tumor development, metastasis, and angiogenesis." (PMID 40136649, 2025). "Classical cytokines IL-6, IL-8, and TGF-β1 were the most studied molecules in patients with lung cancer treated with radiotherapy and were associated with poor survival and increased risk of radiation-induced toxicity." (PMID 40746594, 2025). "On the other hand, USP24 stabilizes p300, increasing histone H3 acetylation at the IL-6 promoter, which enhances IL-6 expression in M2 macrophages and promotes lung cancer progression." (PMID 40375990, 2025). "On the other hand, the same study emphasizes how IL-6 promotes tumor growth by favorably regulating it through expressing the cell cycle regulator, CyclinD1, suggesting the pleiotropic roles of IL-6 in lung cancer progression and development." (PMID 41376623, 2025). "Recent studies showed that baseline CRP and IL-6 levels predicted depressive symptoms during chemotherapy in a prospective cohort of lung cancer patients." (PMID 41149069, 2025). "For example, in non‐small cell lung cancer, there are ongoing clinical trials inhibiting IL6, LIF, or IL1β (NCT04691817, NCT05061550, and NCT03631199, respectively) to address immunotherapy resistance." (PMID 39918251, 2025). "A more recent study demonstrated that circFOXK2 works through the miR-149-3p/IL-6 axis to promote the tumorigenesis of non–small cell lung cancer (NSCLC)." (PMID 40233410, 2025). "Our results emphasize the value of further examinations into strategies that block IL-6 to abolish lung cancer migration and osteolytic bone metastasis in smokers with lung cancer." (PMID 38993553, 2024). "In a subsequent verification within the prospective Prostate, Lung, Colorectal, and Ovarian Cancer Screening Trial, they found that an increase in IL-6 levels was exclusively connected to lung cancer cases diagnosed within two years of blood sampling." (PMID 38339264, 2024). "In lung cancer, IL-6 mediates interactions between cancer cells and microglia via Jak2/STAT3 signaling, aiding brain metastasis, a significant mortality driver." (PMID 39286635, 2024).
lung carcinoma (continued). "Both The Cancer Genome Atlas (TCGA) database and our clinic samples demonstrated elevated expression of the osteolytic factor IL-6 in ever-smokers with bone metastasis among lung cancer patients." (PMID 38993553, 2024). "IL-6 is also related to TGF-β1and EMT, which is linked to cisplatin drug resistance in lung cancer,while gemcitabine resistance is linked to IL6 family protein oncostatinM and hypoxia." (PMID 38967485, 2024). "Previous studies have linked elevated levels of C-reactive protein, IL-6, IFN-γ, and IL-1β to an increased risk of lung cancer." (PMID 39015494, 2024). "It has been shown that resveratrol effectively inhibits the properties of lung cancer stem cells, down-regulates the Wnt/β-catenin signaling pathway, reduces the level of IL-6, and inhibits the development of lung cancer through multi-targeting." (PMID 38421832, 2024). "Brain-metastatic lung cancer cells secrete IL-6, prompting microglia’s M2 polarization, which facilitates metastatic colonization." (PMID 39286635, 2024). "Here, we identified a microenvironment with high IL-6 expression in lung cancer, and TAMs are one of the major sources of IL-6." (PMID 38424624, 2024). "IL-6 is considered a major driver of disease severity in TB and a key player in the tumorigenesis mechanisms in Lung cancer." (PMID 38836056, 2024). "In lung cancer, IL-6 and IL-17 upregulate RORγt through STAT3 signaling mechanisms in order to produce IL-17 isoforms, IL-17A/F." (PMID 38279220, 2024). "Taken together, these reports and our findings suggest that pharmacological and genetic blockade of IL-6 is a novel avenue for treating smoke-induced lung cancer-related osteolytic bone metastasis." (PMID 38993553, 2024). "For instance, elevated serum levels of IL-6 and IL-8 have been correlated with reduced survival durations in lung cancer patients." (PMID 38276239, 2024). "IL-6 levels exhibited a marked rise from 3.8 ± 0.9 pg/mL to 8.5 ± 2.1 pg/mL (p < 0.001), underscoring its role as a key inflammatory marker in lung cancer progression." (PMID 39816276, 2024). "The interaction of IL-6 with TGF-β, particularly on lung cancer cells, underscores its important role in tumor progression, exemplified by IL-6-mediated chemoresistance through TGF-β-induced EMT." (PMID 39834587, 2024). "Our cellular experiments revealed that benzo[α]pyrene (B[α]P) and cigarette smoke extract (CSE) promoted IL-6 production and cell migration in lung cancer." (PMID 38993553, 2024). "In Kowalski’s study, they analyzed bronchoalveolar lavage fluid (BALF) and serum concentrations of IL-6 for the same lung cancer patients before the occurrence of CIPs and after the onset of CIPs." (PMID 38202262, 2024). "This study focuses on evaluating serum parathyroid hormone (PTH), C-reactive protein (CRP), lipid profile parameters, and interleukin-6 (IL-6) in relation to the stages of lung cancer, exploring their potential as biomarkers for assessing disease severity." (PMID 39816276, 2024). "The IL-6 cytokine has been described as having an important role in the development of malignant tumors, including in the growth of lung cancer-like tissue, as well as in the metastasis of malignant lung tumors." (PMID 38891915, 2024). "We found that high IL-6 expression was related to worse overall survival (OS) in lung cancer patients (P = 0.0032)." (PMID 38424624, 2024). "CHI3L1 regulates the IL-13 signaling pathway through IL-13Rα2, leading to increased secretion of cytokines, such as IL-1β and IL-6, which can influence inflammation in lung cancer." (PMID 38177294, 2024). "Our results suggest that cigarette smoke enhances the PI3K/Akt-activating NF-κB signaling pathways to facilitate IL-6 synthesis and cell motility in lung cancer cells." (PMID 38993553, 2024). "In our study, we found that a microenvironment with high IL-6 expression in lung cancer was able to activate the JAK2/STAT3 pathway in TAMs, and STAT3, a transcription factor, was able to promote C/EBPβ expression." (PMID 38424624, 2024).